CYP2B6 (cytochrome P450 family 2 subfamily B member 6)
Diseases named in the same sentence as CYP2B6 in open-access papers (continued):
Sharing a sentence is not in itself a finding about the gene and the disease.
Thrombocytopenia (4 papers, 2021 to 2023). A reduction in the number of circulating thrombocytes. "Decreased risk of drug toxicity (neutropenia, thrombocytopenia, anemia, mucositis and alopecia) was observed in carriers of CYP2B6 *1/*6 and CYP2B6*6/*6 genotypes." (PMID 34322158, 2021). "The prevalence of severe thrombocytopenia (grades 3 and 4) was also higher in normal/rapid CYP2B6 metabolizers than in poor/intermediate metabolizer patients (Chi2: 5.588, N = 50, P = 0.018)." (PMID 37479763, 2023). "After multiple cycles of cyclophosphamide treatments, the incidence of liver injury and hematologic toxicities, including lymphopenia, thrombocytopenia and monocytopenia, but not excretory system (kidneys, urinary bladder) toxicities were associated with the patients’ CYP2B6 metabolizer phenotype." (PMID 37479763, 2023). "We hypothesize that through the inhibition of CYP2B6, CYP2C9, CYP2C9, CYP2C19, and CYP3A4, Schisandra chinensis preparations increased the concentration and side effects of bupropion (thrombocytopenia and generalized arthralgia), amitriptyline (delirium), and fluoxetine (dysuria)." (PMID 37829299, 2023).
Cirrhosis (3 papers, 2006 to 2021). A chronic disorder of the liver in which liver tissue becomes scarred and is partially replaced by regenerative nodules and fibrotic tissue resulting in loss of liver function. "In terms of Vmax, CYP2A6, CYP2B6, CYP2C9, CYP2D6, CYP2E1, and CYP3A4/5 were increased, while the Vmax values of CYP1A2 and CYP2C8 were decreased in both the cirrhosis and fibrosis groups compared to control subjects." (PMID 27203676, 2016). "Compared with controls, the Km values of CYP1A2, CYP2A6, CYP2B6, CYP2C8, CYP2C19, CYP2E1, and CYP3A4/5 were higher in both in fibrosis and cirrhosis groups." (PMID 27203676, 2016).
acute leukemia (2 papers, 2020 to 2025). A clonal (malignant) hematopoietic disorder with an acute onset, affecting the bone marrow and the peripheral blood. "We investigated associations of CYP2B6 c.516G>T polymorphism with acute leukemias (AL) in Han Chinese." (PMID 32119768, 2020). "The aim of this study was to investigate potential associations between CYP2B6 c.516G>T polymorphism and the occurrence and prognosis of acute leukemias (AL) in the Han population of Northwest China." (PMID 32119768, 2020).
alcoholic liver diseases (2 papers, 2021). A disorder caused by damage to the liver parenchyma due to alcohol consumption. "Alcoholic liver disease and primary biliary cholangitis were involved in the most prominent changes in the protein abundances, with downregulation of 6 (CYP1A2, CYP2C8, CYP2D6, CYP2E1, CYP3A4, UGT2B7) and 5 (CYP1A1, CYP2B6, CYP2C8, CYP2E1, CYP3A4) significantly downregulated enzymes, respectively." (PMID 34575411, 2021). "However, in Caucasians, no statistically significant changes in CYP2B6 expression in alcoholic liver disease, as well as in hepatitis C virus-induced liver damage and primary sclerosing cholangitis, were observed." (PMID 34117631, 2021).
autoimmune disease (2 papers, 2018 to 2024). A disorder resulting from loss of function or tissue destruction of an organ or multiple organs, arising from humoral or cellular immune responses of the individual to their own tissue constituents. "We found that leflunomide (LEF) and its main metabolite teriflunomide (TER), both used for autoimmune diseases treatment, induce the prototype CAR target gene CYP2B6 in primary human hepatocytes." (PMID 30364229, 2018).
Breast Tumors (2 papers, 2004 to 2014). "The nature of the protein bands recognized by anti-CYP2B6 antibodies in breast tumors is being studied." (PMID 25526449, 2014). "Although it has previously been shown that ERs regulate CYP2B6 expression in vitro through direct binding to an estrogen responsive element located in the CYP2B6 promoter, we have not detected a protein product of the anticipated molecular weight in breast tumors." (PMID 25526449, 2014). "CYP2C9 (n=9) was present in all tested breast tumour samples, too, while CYP2B6 (n=10) protein could not be detected." (PMID 14970873, 2004). "Additionally, CYP2B6 detection with an antibody strongly reacting with human cDNA-expressed CYP2B6 (detection limit approximately 0.2 pmol) showed no positive immunostaining in all tested breast tumour samples (10 out of 11)." (PMID 14970873, 2004).
glioma (2 papers, 2018 to 2021). A benign or malignant brain and spinal cord tumor that arises from glial cells (astrocytes, oligodendrocytes, ependymal cells). "Our results suggest that it is necessary to explore the CYP2B6 induction by nicotine in pediatric glioma tumors." (PMID 29914177, 2018). "Since we found high tumor CYP2B1 protein expression in the animal model, we explored CYP2B6 protein levels in pediatric gliomas." (PMID 29914177, 2018). "Since we found CYP2B1 over-expression in the animal glioma model, we explored the expression of the homologous enzyme (CYP2B6) in samples from human gliomas." (PMID 29914177, 2018). "We found high basal expression of the enzyme in tumor cells; thus, we also explored the expression of CYP2B6 in pediatric glioma samples." (PMID 29914177, 2018). "In this study, we explored the induction of the Cyp2b1 (homologous to CYP2B6) by nicotine in an animal rat model with glioma." (PMID 29914177, 2018). "We explored CYP2B6 expression in seven glioma samples, five samples were obtained from male patients and two from females, with an age range between 3–14 years and pathological diagnoses of glioma grade I-IV." (PMID 29914177, 2018). "Due to the low number of pediatric glioma samples analyzed in this study, a more detailed study must be conducted in order to elucidate if CYP2B6 induction as a pre-treatment could result in a better response to CPA." (PMID 29914177, 2018). "Moreover, CYP2B6 expression was explored in samples of pediatric gliomas, ranging from grade I to IV." (PMID 29914177, 2018). "Induction of the CYP2B6 in pediatric gliomas with lower expression of the enzyme, could be an alternative to improve the antitumoral effect of CPA treatment." (PMID 29914177, 2018). "The animal model reported in this work could be used to explore changes in CPA pharmacokinetics and anti-tumor activity when pre-treatment to induce CYP2B6 is used, since the model has high basal expression of CYP2B6 in the tumor tissue as occurs in pediatric gliomas." (PMID 29914177, 2018). "The presented results could also be relevant in order to choose the best chemotherapeutic option for pediatric gliomas treatment, however, it is necessary to perform more studies to know if CYP2B6 expression could be used as a CPA-based chemotherapy response marker." (PMID 29914177, 2018). "As expected, in our model, nicotine treatment did not modify Cyp2b1 (homologous to CYP2B6 in the rat) gene expression in the liver of healthy or glioma animals." (PMID 29914177, 2018).
gliosarcoma (2 papers, 2004 to 2010). A rare histological variant of glioblastoma (WHO grade IV) characterized by a biphasic tissue pattern with alternating areas displaying glial and mesenchymal differentiation (WHO). "P450-reductase and CYP2B6 gene cotransferred into gliosarcoma cells significantly increased the cyclophosphamide and ifosfamide activation." (PMID 14970873, 2004). "Previously, we reported that stable expression of the pan-caspase inhibitor p35 in 9L gliosarcoma cells engineered to express CYP2B6 delayed, but did not prevent death of the P450-expressing tumor cells, thereby increasing overall CPA activation and cancer cell death." (PMID 20836875, 2010).
Hepatic failure (2 papers, 2023 to 2025). "The protein levels of CYP2B6 were not affected by the stage of liver failure." (PMID 36901973, 2023).
hepatitis C (2 papers, 2012 to 2021). "Our results indicate that Hepatitis C infection and CYP2B6*6 genotype are risk factors for the development of DILI." (PMID 22808112, 2012).
hepatotoxicity (2 papers, 2018 to 2019). Toxicity that causes injury to the liver or impairs the liver function. "CYP2B6 516GT+TT combined genotype revealed a risk for acquisition of ARV‐associated hepatotoxicity and its severity in combined alcohol and nevirapine users (OR = 1.67, p = 0.37; OR = 4.00, p = 0.46, respectively)." (PMID 30864294, 2019). "Similarly, presence of CYP2B6 516GT genotype among alcohol users resulted in the modulation of risk for acquisition of ARV‐associated hepatotoxicity (OR = 2.03, p = 0.17)." (PMID 30864294, 2019). "Patients with hepatotoxicity using tobacco had a higher prevalence of genotypes CYP2B6 516GT, 516TT, 516GT+TT as compared to healthy individuals (28.57% vs. 25.93%; 57.14% vs. 29.63%; 85.71% vs. 55.56%)." (PMID 30864294, 2019). "While comparing between HIV patients with and without hepatotoxicity, CYP2B6 516TT genotype, taking alcohol and male HIV patients with hepatotoxicity showed a risk for ARV‐associated hepatotoxicity (OR = 1.79, p = 0.27; OR = 1.91, p = 0.63; OR = 1.90, p = 0.16, respectively)." (PMID 30864294, 2019).
injury (2 papers, 2021 to 2024). Damage inflicted on the body as the direct or indirect result of an external force, with or without disruption of structural continuity. "This meta-analysis illustrated that CYP2B6 *6 and *1 was significantly associated with EFV-induced liver injury and NVP-induced liver injury in PLHIV, respectively." (PMID 39604537, 2024).
schizophrenia (2 papers, 2017 to 2025). A major psychotic disorder characterized by abnormalities in the perception or expression of reality. "We investigated the effects of age, sex, and genetic polymorphisms in CYP isoforms (CYP1A2, CYP2B6, CYP2C19, CYP2D6, and CYP3A5) and drug transporters (ABCG2 and SLCO1B1) on the plasma concentrations of clozapine, N‐desmethylclozapine, and clozapine N‐oxide in Japanese patients with schizophrenia." (PMID 40740505, 2025). "DNA was isolated from the peripheral blood samples of 27 patients with schizophrenia receiving clozapine maintenance treatment, and the pharmacokinetics‐related genes (CYP1A2, CYP2B6, CYP2C19, CYP2D6, CYP3A5, ABCG2, and SLCO1B1) were genotyped." (PMID 40740505, 2025).
alcohol use disorder (1 paper, 2025). "However, elevated levels of CYP2B6 are observed in specific brain regions of individuals with a history of smoking and alcohol use disorder, suggesting the inducibility of CYP2B6 in the human brain." (PMID 40126262, 2025).
asthenia (1 paper, 2023). Clinical sign or symptom manifested as debility, or lack or loss of strength and energy. "The association between CYP2B6 RMs and asthenia incidence can be considered spurious; should CYP2B6 metabolize desvenlafaxine, a lower rate of ADRs should be expected in individuals with a higher metabolic capacity." (PMID 36817149, 2023). "CYP2B6 RMs showed a higher incidence of asthenia (13% compared to 0% in NMs, IMs and PMs, p = 0.038)." (PMID 36817149, 2023).
B-cell non-Hodgkin lymphoma (1 paper, 2016). The most common type of non-Hodgkin lymphoma. "A recent study reported a link between CYP2B6*6 allele and reduced CP clearance in children with B-cell non-Hodgkin’s lymphoma." (PMID 27618021, 2016).
cardiac arrhythmia (1 paper, 2013). Any disturbances of the normal rhythmic beating of the heart or MYOCARDIAL CONTRACTION. "Additionally, CYP2B6 slow metabolizers exhibit a reduced ability to metabolize S-methadone and were associated with an increased risk of a prolonged QT interval (OR = 4.5), which may increase the risk of cardiac arrhythmias and sudden death." (PMID 24455721, 2013).
childhood cancer (1 paper, 2021). "In conclusion, adult female CCSs carrying the CYP3A4*3 allele appear to have a five-fold lower ovarian function after treatment for childhood cancer, and CYP2B6*2 may have a protective effect on AMH levels in patients receiving CED scores of 8000mg/m2 or more." (PMID 34572825, 2021).
chronic myeloid leukemia (1 paper, 2022). "Olverembatinib (HQP1351) is a third-generation BCR-ABL tyrosine kinase inhibitor for the treatment of chronic myeloid leukemia (CML) (including T315I-mutant disease), exhibits drug-drug interaction (DDI) potential through cytochrome P450 (CYP) enzymes CYP3A4, CYP2C9, CYP2C19, CYP1A2, and CYP2B6." (PMID 36582520, 2022).
dyslipidaemia (1 paper, 2025). "We hypothesised that CYP2B6 slow metabolisers treated with efavirenz and isoniazid will have increased efavirenz concentrations with an increased risk of efavirenz-related neurotoxicity, hepatotoxicity, dyslipidaemia, and dysglycaemia." (PMID 40182085, 2025).
glomerulonephritis (1 paper, 2014). A renal disorder characterized by damage in the glomeruli. "Our results showed that cyclophosphamide-treated glomerulonephritis patients had a 4-fold higher expression of CYP2B6 (2.07 ± 2.94 vs. 0.45 ± 0.5; p = 0.01) than mycophenolate-treated patients." (PMID 24548980, 2014).
Hepatitis B (1 paper, 2013). "Univariate linear regression analysis identified the following variables as predictors (r2, p value) of efavirenz plasma level at week 16; CYP2B6*6 genotype (17.9%, p<0.0001), country (2.5%, p<0.0001), coinfection with Hepatitis B at recruitment (2.6%, p = 0.003)." (PMID 23861838, 2013).
hepatoblastoma (1 paper, 2016). Hepatoblastoma (HB) is a malignant hepatic tumor and is the most common pediatric liver cancer. "The mRNA expression levels of CYP2B6, SPON1, and GSG1L in human hepatoblastoma (HepG2) cells were measured after 24 h of exposure to CAR agonists." (PMID 27010727, 2016).
Hyperbilirubinemia (1 paper, 2021). An increased amount of bilirubin in the blood. "Our findings suggest that after treatment with ATV or EFV, UGT1A1*28 and CYP2B6 c.516G>T (rs3745274) genetic polymorphisms influence the appearance of moderate-to-severe hyperbilirubinemia and CNS toxicity, respectively." (PMID 34093191, 2021).
leukopenia (1 paper, 2022). "Except for the coding region, a study in Japan found that CYP2B6 (g.−2320T > C, g.18492T > C, and g.−750T > C) in the non-coding region was also significantly associated with ADR (including leukopenia) of CYC." (PMID 35935867, 2022).
lymphopenia (1 paper, 2023). Reduction in the number of lymphocytes. "Grade 3 lymphopenia occurred more frequently in patients with normal/rapid function than in those with poor/intermediate CYP2B6 function (Chi2: 6.044, N = 47, P = 0.015)." (PMID 37479763, 2023).
lymphoproliferative disorders (1 paper, 2024). "This implies that males may be more susceptible than females to the development of such lymphoproliferative disorders due to the CYP2B6 enzyme’s declining activity." (PMID 38560574, 2024).
mastocytosis (1 paper, 2020). A clonal myeloproliferative neoplasm characterized by the proliferation and accumulation of neoplastic mast cells in one or multiple organs or organ systems. "Four SNPs were more prevalent (in ABCA2, OTX2-AS1, HLA-V, and PDE4DIP genes) and 5 were less prevalent (in RPTN, CYP2B6, OR51Q1, FTCD, and rs9828758 near RP11 genes) in mastocytosis patients compared to a control cohort." (PMID 32752121, 2020).
medulloblastoma (1 paper, 2022). A malignant, invasive embryonal neoplasm arising from the cerebellum. "HIF1α promoted drug resistance in human medulloblastoma by inhibition of CYP2B6, CYP3A4 and CYP3A5 expression, which in turn resulted in decreased conversion of CPA and IFA into their active forms and thus to diminished cytotoxicity." (PMID 35355718, 2022).
neuroblastoma (1 paper, 2023). Neuroblastoma (NB) is the most common solid, extracranial childhood tumor. "In these neuroblastoma patients, a significant association of CYP2B6 genetic variants with liver injury and hematologic toxicity was observed, but not with renal and bladder injury." (PMID 37479763, 2023). "In conclusion, mild hepatotoxicity was observed in patients with neuroblastoma receiving cyclophosphamide therapy, which was more frequent in patients with normal/rapid CYP2B6 metabolizing capacity than in those with poor/intermediate CYP2B6 phenotypes." (PMID 37479763, 2023). "The major aim of the present study was to determine the role of CYP2B6 pharmacogenetic variability and patient-specific phenoconverting factors, such as age and sex, in the development of toxic events in pediatric patients with neuroblastoma undergoing cyclophosphamide therapy." (PMID 37479763, 2023). "In the present study, the contribution of pharmacogenetic variability in CYP2B6 and CYP2C19 to treatment efficacy and cyclophosphamide-induced side effects was evaluated in pediatric patients with neuroblastoma." (PMID 37479763, 2023). "The aim of the study was to reveal the contribution of pharmacogenetic variability in CYP2B6 and CYP2C19 to the treatment efficacy and cyclophosphamide-induced side effects in pediatric neuroblastoma patients under cyclophosphamide therapy (N = 50)." (PMID 37479763, 2023). "Although, neuroblastoma considered to be the most prevalent extracranial solid tumour malignancy in childhood, cyclophosphamide-induced toxicity related to the patients’ CYP2B6 and CYP2C19 status has not been extensively investigated in patients with neuroblastoma." (PMID 37479763, 2023).
non-Hodgkin lymphoma (1 paper, 2021). Distinct from Hodgkin lymphoma both morphologically and biologically, non-Hodgkin lymphoma (NHL) is characterized by the absence of Reed-Sternberg cells, can occur at any age, and usually presents as a localized or generalized lymphadenopathy associated with fever and weight loss. "Induction of CYP2B6 by a selective activator (e.g., CITCO) facilitates the bioactivation of CPA to 4-OH-CPA and improves the therapeutic outcome of CHOP (cyclophosphamide–doxorubicin–vincristine–prednisone) chemotherapy against non-Hodgkin lymphoma." (PMID 34887762, 2021).
opioid dependence (1 paper, 2014). "Cytochrome p450 2B6 (CYP2B6) has also been commonly studied in opioid dependence and drug response, and as such will be another focus of this study." (PMID 24489693, 2014).
osteosarcoma (1 paper, 2020). A usually aggressive malignant bone-forming mesenchymal neoplasm, predominantly affecting adolescents and young adults. "In conclusion, this study identified statistically significant associations for a genetic variant in SULT1E1 with MTX plasma levels and three genetic variants in CYP2B6 and CYP4F8 with thrombocyte counts after HD-MTX infusion in osteosarcoma patients." (PMID 32903464, 2020).
prostate tumor (1 paper, 2021). "CYP3A4 and CYP2B6 are also inhibited by bergamottin but are not expressed in normal and prostate tumor cells." (PMID 34570813, 2021).
psychosis (1 paper, 2016). "Another reported case of a 12-year-old girl presenting with psychosis associated with long term EFV use with genetic analysis showing a heterozygous CYP2B6 c.516G/T genotype." (PMID 26831894, 2016).
sleep disorder (1 paper, 2013). A change from the patient's baseline sleeping pattern, in the hours slept and/or an alteration/dysfunction in the stages of sleep. "Though not statistically significant, we observed a tendency of CYP2B6*6 genotype to be associated with relatively higher incidence of sleep disorder and hallucination by second week of initiation of therapy." (PMID 23734829, 2013).
Stevens-Johnson syndrome (1 paper, 2021). Stevens-Johnson syndrome is a limited form of toxic epidermal necrolysis characterized by destruction and detachment of the skin epithelium and mucous membranes involving less than 10% of the body surface area. "The variant allele of CYP2B6*18 and CYP2B6*4 were associated with the occurrence of Stevens-Johnson syndrome (SJS) among HIV patients." (PMID 34322158, 2021).
substance abuse (1 paper, 2014). The use of a drug for a reason other than which it was intended or in a manner or in quantities other than directed. "Among the articles reviewing the association between the CYP2B6*6 haplotype or the ABCB1 (rs1045642) SNP and continued illicit substance abuse among MMT patients, only two articles provided data on each gene of interest." (PMID 24489693, 2014).